DROSHA (drosha ribonuclease III)
Description:
Ribonuclease III double-stranded (ds) RNA-specific endoribonuclease that is involved in the initial step of microRNA (miRNA) biogenesis. Component of the microprocessor complex that is required to process primary miRNA transcripts (pri-miRNAs) to release precursor miRNA (pre-miRNA) in the nucleus. Within the microprocessor complex, DROSHA cleaves the 3' and 5' strands of a stem-loop in pri-miRNAs (processing center 11 bp from the dsRNA-ssRNA junction) to release hairpin-shaped pre-miRNAs that are subsequently cut by the cytoplasmic DICER to generate mature miRNAs. Involved also in pre-rRNA processing. Cleaves double-strand RNA and does not cleave single-strand RNA. Involved in the formation of GW bodies. Plays a role in growth homeostasis in response to autophagy in motor neurons (By similarity).
Synonyms: RN3; RNASE3L; RNASEN; Etohi2; HSA242976; RANSE3L
Tractability: PROTAC: ubiquitination databases record sites on it; its protein half-life has been measured.
Safety:
Unwanted effects reported when the protein is acted on. In parentheses: how it was acted on, where the effect was seen, and who reports it.
drug toxicity (source: ClinPGx)
Gene: Protein-coding gene on chromosome 5 (31,400,494 to 31,533,186, reverse strand). Ensembl gene ENSG00000113360.
Subcellular location: Nucleus; Nucleus, nucleolus; Cytoplasm
Subcellular location (Human Protein Atlas): Nucleoplasm; Cytosol
Pathways (Reactome):
Gene expression (Transcription): MicroRNA (miRNA) biogenesis
Gene Ontology:
Molecular function: DEAD/H-box RNA helicase binding; lipopolysaccharide binding; primary miRNA binding; protein binding; protein homodimerization activity; R-SMAD binding; ribonuclease III activity; RNA binding; SMAD binding; RNA endonuclease activity
Biological process: defense response to Gram-negative bacterium; defense response to Gram-positive bacterium; primary miRNA processing; pre-miRNA processing; miRNA processing; positive regulation of gene expression; RNA processing; rRNA processing
Cellular component: microprocessor complex; nucleoplasm; nucleus; cytoplasm; glutamatergic synapse; nucleolus; organelle; postsynaptic density
Genetic constraint (gnomAD): Loss-of-function variants: 51 observed, 164.98 expected, observed/expected ratio (o/e) 0.31, 90% interval 0.25 to 0.39. The upper end of that interval is the gene's LOEUF score, 0.39, which puts it in group 1 of 6, group 1 being the genes least tolerant of losing a copy. Missense variants: 1,157 observed, 1,665.4 expected, observed/expected ratio (o/e) 0.69, 90% interval 0.66 to 0.73. Synonymous variants: 493 observed, 565.83 expected, observed/expected ratio (o/e) 0.87, 90% interval 0.81 to 0.94.
Homologues: Orthologues: dog DROSHA (99% identical), chimpanzee DROSHA (98% identical), macaque DROSHA (97% identical), rat Drosha (96% identical), mouse Drosha (96% identical), pig DROSHA (95% identical), rabbit DROSHA (94% identical), guinea pig DROSHA (91% identical), tropical clawed frog drosha (76% identical), zebrafish drosha (75% identical), Drosophila melanogaster drosha (44% identical), Caenorhabditis elegans drsh-1 (25% identical).
Diseases named in the same sentence as DROSHA in open-access papers:
DROSHA is named in the same sentence as 100 diseases in open-access papers, as found by Europe PMC text mining. Sharing a sentence is not in itself a finding about the gene and the disease. The quoted sentences say what the papers report.
breast cancer (24 papers, 2012 to 2024). A primary or metastatic malignant neoplasm involving the breast. "Another report also associated rs2291109 (A > T) in DROSHA with increased breast cancer susceptibility [Odds ratio (OR) = 0.81; 95% Confidence Interval (CI) 0.66–0.99] in Chinese patients." (PMID 30897768, 2019). "It has reported that DROSHA rs644236 TT genotype and rs7737174 AA genotype were associated with breast cancer risk in postmenopausal women." (PMID 24312312, 2013). "Moreover, multiple SNPs in DROSHA mutations are common in diverse human malignancies, including Wilms tumor, esophageal cancer, and breast cancer." (PMID 36672288, 2023). "Similarly, DROSHA*rs10719 increases the risk of breast cancer (OR = 1.39) while decreasing the susceptibility of developing CLL (OR = 0.58)." (PMID 36672288, 2023). "The loss of DROSHA has been documented in both endometrial cancer and breast cancer." (PMID 34914716, 2021). "A case-control study of the SNPs rs644236 (C > T) and rs7737174 (A > G) within the DROSHA gene demonstrated increased risk of developing breast cancer (OR = 1.27; CI 0.94–1.73, and OR = 1.63; CI 1.01–2.64, for rs644236 and rs7737174, respectively) in Korean post-menopausal women." (PMID 30897768, 2019). "We also found the variant allele of DROSHA rs874332 was associated with poor OS in breast cancer." (PMID 22639842, 2012). "Further, differences in expression of DICER1, AGO and DROSHA, all crucial to miRNA biosynthesis, between breast cancer subtypes have been shown." (PMID 31581940, 2019). "Over expression of DROSHA was shown to effect cell proliferation and predicted poor prognosis in esophageal cancer, ovarian cancer, breast cancer, and cervical cancer." (PMID 24312312, 2013). "In breast cancer, down regulation in DROSHA and/or DICER was preferentially observed in distinct subgroups of breast cancer." (PMID 22639842, 2012). "Our study presents evidence linking the DROSHA rs10719 and DICER rs3742330 polymorphisms to an elevated risk of breast cancer in an Egyptian cohort, suggesting that these variants may play a role in miRNA dysregulation during breast tumorigenesis." (PMID 39329954, 2024). "Aurora A-induced oncogenic m6A modification acts as a key regulator of DROSHA in breast cancer." (PMID 34715887, 2021). "Moreover, expression of DROSHA has been recently shown to be impaired in breast cancer patients, possibly in the attempt to stimulate HR, although the molecular mechanisms by which this may be relevant for cancer development remain to be defined." (PMID 33558311, 2021). "For instance, in breast cancer stem-like cells, AURKA strengthens the binding of IGF2BP2 to stabilize m6A-modified DROSHA, resulting in the maintenance of breast cancer stemness." (PMID 38281999, 2024). "In breast cancer, RNase III DROSHA was reported to interact with β-Catenin to transactive STC1 in an RNA cleavage-independent manner, contributing to cancer stem cell properties." (PMID 34315512, 2021). "Dysregulation of DROSHA and DGCR8 has been observed in many cancers such as epithelial skin cancer, breast cancer and ovarian cancer." (PMID 27957388, 2016). "DROSHA RNase III was upregulated in a number of cancers and interacted with β-catenin to activate stanniocalcin 1 (STC1) in an RNA cleavage-independent manner, which in turn contributed to the properties of breast cancer stem-like cells (BCSCs)." (PMID 35721510, 2022). "In breast cancer, aurora kinase A (AURKA) positively regulates METTL14 protein expression by inhibiting its ubiquitylation‐mediated degradation to elevate DROSHA m6A content to improve DROSHA mRNA stability in breast cancer stem‐like cells." (PMID 34904301, 2022). "Indeed, it has been shown that sex-steroids regulate the protein expression of DICER1, DROSHA, XPO5, and Argonaute (AGO) proteins in human breast cancer and endometrium." (PMID 33477993, 2021).
breast cancer (continued). "On the one hand, m6A enhances processing of many, if not all, miRNAs in breast cancer cells, and can be regarded as a general mechanism; this methylation promotes the binding of DROSHA to the primary miRNA." (PMID 31031083, 2019). "Interestingly, METTL14 can enhance DROSHA mRNA stability by catalyzing the m6A modification, indicating that targeting the METTL14-DROSHA-β-Catenin axis might impair breast cancer progression." (PMID 34315512, 2021). "After that, the highly expressed DROSHA interacts with β-Catenin to transactivate stemness gene STC1 in an RNA cleavage-independent manner, promoting breast cancer stem cell (BCSC) properties and mediating BC cell proliferation." (PMID 38711100, 2024). "MiR-1254 was suggested as a serum-based miRNA biomarker for early-stage lung cancer and in contrast to canonical miRNAs, its biogenesis is independent of DROSHA; miR-1254 expression enhancement may re-sensitize tamoxifen-resistant breast cancer cells to tamoxifen." (PMID 28589857, 2017).
Wilms tumor (19 papers, 2015 to 2025). An embryonal neoplasm characterized by the presence of epithelial, mesenchymal, and blastema components. "The single missense variant E1147K, which affects the metal binding function of DROSHA, has been identified in Wilms tumor, which is also associated with DICER1 syndrome." (PMID 40940982, 2025). "Somatic mutations of DROSHA have been shown to be frequent and underlie high risk of Wilms' tumors, and DROSHA depletion has been reported to be implicated in the promotion of a migratory phenotype in lung cancer cells." (PMID 33558311, 2021). "Multiple components of the miRNA biogenesis pathway are mutated in pediatric Wilms tumors, including DROSHA, which is down-regulated in around 12% of cases." (PMID 34914716, 2021). "DROSHA is frequently mutated in Wilms tumors, and mature miRNAs are globally downregulated in those tumors." (PMID 32138313, 2020). "It has not been yet identified in the functions of other mutations, such as the missense mutation and nonsense mutation of the DROSHA gene found in Wilms tumors." (PMID 32138313, 2020). "Interestingly, these two tumors (Wilms tumor and pineoblastoma) also harbor DROSHA variants, which are also involved in the RNA-silencing pathway." (PMID 40940982, 2025). "Somatic mutations in DROSHA are frequently found in Wilms’ tumor." (PMID 39457367, 2024). "Wilms’ tumor has been associated with a germline DROSHA variant, R967W, suggesting that such mutations could potentially predispose individuals to certain tumors." (PMID 39457367, 2024). "Interestingly, the occurrence of DROSHA mutations in Wilms' tumor coincides with the occurrence of mutations in SIX1 and SIX2, transcription factor genes that are also frequently mutated in the tumor." (PMID 33406242, 2021). "Furthermore, mutations in miRNA processing enzymes DICER1 or DROSHA are linked with Wilms tumor, indicating the crucial role of miRNAs in the differentiation of mesenchymal stem cells during nephrogenesis and the development of Wilms tumors." (PMID 37345170, 2023). "Mutational analysis has shown that DROSHA and DICER1 mutations, commonly found in Wilms tumors, impair miRNA processing." (PMID 39473825, 2024). "Among the miRNA-processing genes, mutations in DROSHA, DGCR8, DICER1, TARBP2, and XPO5 (encodes exportin 5) have been reported in treatment-naive and neoadjuvant chemotherapy-treated Wilms tumors." (PMID 35531954, 2022). "Accordingly, in the Wilms tumor cases with lower DROSHA expression, TSS-miRNAs, including miR-320a, miR-484, and mirtron miR-877 are up-regulated." (PMID 34914716, 2021). "By studying families of patients diagnosed with pineoblastoma and Wilms tumor, they identified DROSHA germline variants in the absence of DICER1 germline variants." (PMID 40940982, 2025). "A recurrent hotspot mutation (E1147K) in a metal-binding (Mg2+) residue of the RNase IIIb domain of DROSHA, which appears to be unique to Wilms tumor, abolishes the catalytic activity of this domain, resulting in incomplete cleavage of pri-miRNAs and reduced miRNA maturation." (PMID 35531954, 2022). "Furthermore, in breast cancer and Wilms tumor, DROSHA down-regulation was coupled with increased expression of Drosha-independent miRNAs." (PMID 34914716, 2021). "With exception of hotspot mutations found in DICER1, we found only a few mutations in other miRNA biogenesis genes, i.e. DROSHA, DGCR8 and XPO5, which have been recently observed in different childhood cancers associated with DICER1 syndrome and in Wilms' tumor." (PMID 33406242, 2021). "Moreover, mutations in typical Wilms tumour genes were identified, such as WT1, DIS3L2, WTX, CTNNB1 and the miRNA-processing genes DROSHA, DGCR8 and DICER1." (PMID 32161258, 2020). "Additionally, the specific hotspot mutations in DROSHA and DGCR8 commonly observed in Wilms' tumor and other childhood cancers were absent in adult cancers." (PMID 33406242, 2021).
lung carcinoma (13 papers, 2010 to 2024). "MYC binding to DROSHA gene promoter accelerated DROSHA transcription, causing elevated miRNA processing in A549 lung cancer cells." (PMID 35885514, 2022). "This gene is a crucial regulator of microRNA expression, and increased expression of DROSHA has been linked to poor prognosis in lung cancer." (PMID 34625038, 2021). "On the other hand, the relative methylation of DROSHA was characterized by 27.1% sensitivity and 82.4% specificity in the differentiation of lung cancer and the control (AUC = 0.532, 95%CI: 0.502–0.561; p = 0.1037)." (PMID 34885248, 2021). "On the other hand, we found decreased methylation within the DROSHA gene promoter in patients with lung cancer, with NSCLC, and with early stages (IA-IIIA) of NSCLC." (PMID 34885248, 2021). "We observed a significant difference in the relative level of DROSHA gene methylation in both regions between the control group and lung cancer patients." (PMID 34885248, 2021). "The results indicate that the assessment of DICER and DROSHA methylation status can potentially be used as a biomarker for the early detection of lung cancer." (PMID 34885248, 2021). "In our work, we found that the degree of methylation of the DICER and DROSHA promoter regions evaluated in liquid biopsy (peripheral blood) differs significantly in lung cancer patients compared to the healthy population." (PMID 34885248, 2021). "DROSHA is involved in the miRNA depletion observed in lung cancer, and alterations in this gene was shown to have a remarkable impact in lung cancer." (PMID 31568528, 2019). "There is a dose-dependent correlation between the copy number categories and the expression of DICER1 and DROSHA in lung cancer (based on TCGA Cancer Genome ATLAS data)." (PMID 26156018, 2015). "Our results also indicate the important role of miRNA biogenesis genes, especially DROSHA, in lung cancer." (PMID 26156018, 2015). "It has been suggested that disturbance in DROSHA gene expression in lung cancer patients may have important clinical implications." (PMID 34885248, 2021). "In our study, we demonstrated that the methylation status of DICER and DROSHA significantly differs in lung cancer patients compared to the healthy population, which in the future may be used as a molecular biomarker of lung cancer." (PMID 34885248, 2021). "However, in contrast to DROSHA, increased expression of DICER1 was associated with longer survival in various cancers including lung cancer." (PMID 26156018, 2015). "Additionally, for our analysis we selected the genomic regions of miR-155 and miR-17 (identified in one meta-analysis), which were consistently associated with poor prognosis of lung cancer, as well as two genes (DICER1 and DROSHA) encoding miRNA processing enzymes." (PMID 26156018, 2015). "To identify possible biomarkers for early detection of lung cancer we assessed the methylation status of genes related to carcinogenesis, DICER and DROSHA, in lung cancer patients and healthy volunteers." (PMID 34885248, 2021). "Ribonuclease III (RNase III) DROSHA and DICER1 have been shown to be downregulated in lung cancer, ovarian cancer, and neuroblastoma, and their level correlates with tumor stage and clinical outcome." (PMID 31097014, 2019). "In this study we analyzed the somatic copy number variation of 14 miRNA genes frequently found to be either over- or underexpressed in lung cancer, as well as two miRNA biogenesis genes, DICER1 and DROSHA, in non-small-cell lung cancer (NSCLC)." (PMID 26156018, 2015). "The aim of our study was to assess the methylation status of the DROSHA and DICER genes (in two subsequent regions according to their locations in promoter sequences) and their usefulness as biomarkers in the detection of lung cancer." (PMID 34885248, 2021).
DiGeorge syndrome (10 papers, 2013 to 2025). "This complex comprises the RNase III enzymes Drosha ribonuclease III (DROSHA) and DiGeorge syndrome chromosomal region (DGCR), which work together to cut every hairpin structure from long pri-miRNA to produce single hairpins called pre-miRNAs which are ~ 55 to 70 nucleotides long." (PMID 38958690, 2024). "Pri-miR-124 then gets converted into pre-miR (70–100 nucleotides) with the help of DROSHA, DiGeorge syndrome chromosomal region 8 (DGCR8), and RNase III." (PMID 37508353, 2023). "The RNAse III DROSHA, in connection with the Microprocessor complex subunit DGCR8 (DiGeorge syndrome critical region 8), cleaves a primary RNA-transcript into a stem-loop precursor of approximatively 70 nucleotides, called pre-miRNA." (PMID 34178993, 2021). "Processing within the nucleus by the enzyme complex of drosha ribonuclease III (DROSHA) and DiGeorge syndrome chromosomal region 8 (DGCR8) releases the pre-miRNA, a double-stranded RNA molecule consisting of the mature miRNA linked to a complementary (star-) strand by a hairpin loop." (PMID 29657307, 2018).
ovarian carcinoma (9 papers, 2012 to 2023). A malignant neoplasm originating from the surface ovarian epithelium. "Aberrant expression of DROSHA at mRNA or protein level was shown to be associated with patient survival and tumor progression in several types of cancer, including pleomorphic adenomas, esophageal cancer, cervical cancer and ovarian cancer." (PMID 25793711, 2015). "Low expression of DROSHA and DICER was associated with decreased survival in ovarian cancer." (PMID 23671264, 2013). "It has been shown that gene sets related to RNase III DROSHA and DICER1 were decreased in ovarian cancer." (PMID 33371881, 2020).